SSX2 (SSX family member 2)
Description:
Could act as a modulator of transcription.
Synonyms: CT5.2; HOM-MEL-40; HD21; MGC3884; MGC15364; MGC119055; CT5.2a; SSX
Tractability: No criterion of Open Targets' tractability assessment is met for any kind of drug.
Gene: Protein-coding gene on chromosome X (52,696,896 to 52,707,178, reverse strand). Ensembl gene ENSG00000241476.
Subcellular location: Nucleus
Subcellular location (Human Protein Atlas): Nucleoli; Nucleoplasm
Gene Ontology:
Molecular function: protein binding
Biological process: regulation of DNA-templated transcription
Cellular component: nucleus
Homologues: Orthologues: mouse Ssxb9 (34% identical), mouse Ssxb8 (33% identical), mouse Ssxb6 (32% identical), mouse Ssxb1 (32% identical), mouse Ssxb10 (32% identical), mouse Ssxb15 (32% identical), rat Ssx2 (32% identical), mouse Ssxb13 (31% identical), mouse Ssxb3 (31% identical), rat Ssx1 (31% identical), mouse Ssxb14 (31% identical), mouse Ssxb5 (30% identical), and 3 more. Paralogues in human: SSX2B (100% identical), SSX3 (90% identical), SSX7 (85% identical), SSX5 (84% identical), SSX4 (79% identical), SSX4B (79% identical), SSX1 (78% identical).
Diseases named in the same sentence as SSX2 in open-access papers:
SSX2 is named in the same sentence as 61 diseases in open-access papers, as found by Europe PMC text mining. Sharing a sentence is not in itself a finding about the gene and the disease. The quoted sentences say what the papers report.
synovial sarcoma (107 papers, 2001 to 2025). "Gene rearrangements can lead to SSX2 fusion genes such as SS18-SSX2, a main oncogenic driver and diagnostic marker in synovial sarcoma, and the more recently identified EWSR1-SSX2 fusion gene in a patient with undifferentiated sarcoma of the bone." (PMID 38596293, 2024). "The transcripts resulting from fusions of the SYT (at 18q11) gene with either SSX1 or SSX2 (both at Xp11) are diagnostic markers for synovial sarcomas." (PMID 34575830, 2021). "Lastly, a fourth patient with MPNST was reclassified as having synovial sarcoma based on detecting an SS18::SSX2 fusion, leading to an evaluation for NY-ESO-1-based T-cell therapy." (PMID 38228904, 2024). "Together, generation of SSX2-FLAG SYO-1 cells provides us with a unique opportunity to dissect endogenous SS18-SSX2 function and gain new insights into synovial sarcoma biology." (PMID 39045458, 2024). "We have recently used the CRISPR/Cas9 technology to insert a FLAG-tag sequence at the 3’ end of the SSX2 gene in human SYO-1 cells (a well-established synovial sarcoma cell line)." (PMID 39045458, 2024). "For example, the COSMIC fusions SS18::SSX1 and SS18::SSX2, known drivers of synovial sarcoma, are in other clusters (C38 and C39), due in part to their higher 5′-FAR." (PMID 37323575, 2023). "Synovial sarcoma is associated with translocation causing a fusion between chromosomes SSX1, SSX2, and SSX4 and chromosome SS18, occurring in more than 90% of synovial sarcoma cases leading to the formation of SSX-SS18 oncogenes." (PMID 38188535, 2023). "Final pathology confirmed the diagnosis of a monophasic synovial sarcoma with a canonical SS18-SSX1/SSX2 gene fusion." (PMID 35422025, 2022). "Lastly, the ssx2 gene, that is, found in the ctag1b/a subnetwork, is involved in 80% of all synovial sarcomas as fusion protein products SSXT-SSX1 or SSXT-SSX2, derived from translocation t (X; 18) (p11.2; q11.2)." (PMID 35664317, 2022). "SYO-1, a synovial sarcoma cell line carrying SS18 (SYT)-SSX2 fusion gene, underwent apoptosis upon treatment with ZSTK474, as determined by emergence of cleaved PARP." (PMID 30416685, 2018). "Compared to their more common soft tissue counterparts the relatively unique features of Scheithauer’s intra-neural synovial sarcomas included over-representation of the monophasic subtype (90%) and SSX2 fusion partner." (PMID 24131748, 2013). "This disease is characterized by a persistent t(X;18)(p11;q11) translocation event that juxtaposes the SYT (SYnovial sarcoma Translocated) gene on chromosome 18 with an SSX gene (either SSX1 or SSX2) on the X chromosome." (PMID 19337376, 2009). "SSX2 may, therefore, be a target in synovial sarcomas, which were SSX2-positive in 25% in our study and which are treated with SSX2-directed cytotoxic T-lymphocytes in the TACTASOM trial (NCT02239861)." (PMID 33287125, 2020). "SS18-SSX1/SSX2/SSX4 fusions were observed in most synovial sarcoma." (PMID 32019274, 2020). "In order to expand the repertoire of antigens that can be targeted by this approach, therefore expanding the number of patients and tumor types that can be treated, we developed a TCR-expressing vector targeting a member of the synovial sarcoma X breakpoint family, SSX2." (PMID 24681846, 2014). "In Synovial Sarcoma (SS), characterized by the fusion of the SS18 gene to either SSX1, SSX2, or SSX4, the expression of FOXM1 associates with poor prognosis and correlates with cell-cycle genes." (PMID 38946804, 2024). "The genetic hallmark of synovial sarcoma is the chromosomal translocation t(X;18)(p11;q11), which leads to a fusion of SS18 (SYT), which encodes a SWI–SNF complex component, to one of the homologues SSX genes (SSX1, SSX2, rarely SSX4), which encodes instead a transcriptional repressor." (PMID 34440844, 2021). "Most cases of synovial sarcoma exhibit a fusion between the SS18 gene and either the SSX1 or the SSX2 gene, creating SS18-SSX1 or SS18-SSX2 gene rearrangements." (PMID 41149817, 2025).
synovial sarcoma (continued). "Synovial sarcoma harbours a pathognomonic t (X; 18) translocation resulting in either SS18::SSX1, SS18::SSX2 or SS18::SSX4 fusion genes." (PMID 40666501, 2025). "It is worth noting that two SSX genes, namely, SSX1 and SSX2, are found to commonly be fused to SS18 in synovial sarcoma patients." (PMID 39045458, 2024). "Fusion of the SYT gene on chromosome 18 with one of three homologous genes, SSX1, SSX2, and SSX4, on the X chromosome results in pathological tissue development of synovial sarcoma." (PMID 39583501, 2024). "Synovial sarcoma (SS) is a soft tissue sarcoma showing variable epithelial differentiation and is characterized by SS18::SSX1, SSX2, or SSX4 fusions." (PMID 36941503, 2023). "The Synovial Sarcoma, X-breakpoint (SSX) family of CTAs comprises six highly similar genes (i.e., SSX1, SSX2, SSX3, SSX4, SSX5 and SSX7) and several pseudogenes." (PMID 36276095, 2022). "For instance, beside the canonical fusion involving SS18 and SSX1 or SSX2, additional fusions involving SSX4 were called in 5/6 synovial sarcomas analyzed with the AMP-FPS panel." (PMID 32351889, 2020). "Ossifying synovial sarcomas demonstrate uniform spindle tumor cells and are positive for cytokeratin, EMA, and TLE1 and reveal t(X;18) with SSX2 involvement." (PMID 32867125, 2020). "The fusion SS18-SSX (SSX1, SSX2, or SSX4) gene produced by a chromosomal translocation, t (X;18) (p11.2; q11.2), is detectable in ~95% of synovial sarcomas." (PMID 32429395, 2020). "On the other hand, synovial sarcoma is known to be well-characterized by a specific translocation resulting in gene fusion of SYT with either SSX1, SSX2, or SSX418." (PMID 31562358, 2019). "Synovial sarcoma is characterized by the translocation t(X;18)(p11;q11), which fuses SS18 (SYT) in chromosome 18 and SSX1, SSX2, or SSX4 (rarely) in chromosome X." (PMID 30487384, 2018). "A specific t(X;18)(p11.2;q11.2) translocation resulting in fusion of genes between SYT, on chromosome 18, and SSX1, SSX2, or rarely SSX4 on chromosome X is detectable in 90% of synovial sarcomas." (PMID 29531545, 2017). "The characteristic t (X: 18)(p11.2; q11.2) translocation of synovial sarcoma fuses the SS18 gene on chromosome 18 to one of three homologous genes, SSX1, SSX2 or SSX4, which cluster on the X chromosome." (PMID 27074562, 2016). "The chromosomal translocation t(X;18)(p11.2;q11.2) is the main cytogenetic event in synovial sarcoma and results in the fusion of the BAF complex member SS18 with one of three highly homologous transcriptional repressor genes, SSX1, SSX2 or SSX4." (PMID 27120803, 2016). "The cytogenetically defined translocation t(X;18)(p11.2;q11.2) found in human synovial sarcoma results in the fusion of the SYT gene on chromosome 18 to SSX1, SSX2, or SSX4 on chromosome X at Xp11.2, leading to the formation of SYT-SSX fusion transcript." (PMID 27069481, 2016). "Usually 90% of the synovial sarcomas demonstrate translocation involving fusion of two genes SYT located on chromosome 18q11 and SSX 1, SSX2 or SSX 4 located on Xp11 breakpoint." (PMID 26101678, 2015). "Synovial sarcoma contains a characteristic translocation (X;18)(p11;q11), representing the fusion of SYT on chromosome 18 with either SSX1, SSX2, or rarely SSX4 on chromosome X." (PMID 25613038, 2015). "This has been particularly true since the discovery of highly specific genetic lesions [t(x;18), SYT-SSX1, SSX2, and SSX4 fusion genes] in synovial sarcoma tumors that clinically distinguish this particular this tumor type." (PMID 24910640, 2014). "Major fusion partners of SS18 in synovial sarcoma are SSX1 and SSX2, and SSX4 has been reported in rare cases." (PMID 24130893, 2013). "The majority of cases of synovial sarcoma contain a t(X;18)(p11.2;q11.2) translocation that results in the fusion of the chromosome 18 gene SYT to three closely related genes SSX1, SSX2 and SSX4 on the X chromosome." (PMID 12592363, 2003).
synovial sarcoma (continued). "To comprehensively interrogate the transcriptomic changes occurring in synovial sarcoma cells upon TAK-981 treatment, we treated HS-SY-II (harboring the SS18::SSX1 fusion) and SYO1 cells (harboring the SS18::SSX2 fusion) with DMSO or TAK-981 and performed bulk RNA sequencing." (PMID 40804185, 2025). "In synovial sarcoma samples, there is a chromosome translocation that results in the replacement of C-terminal 8 amino acids of wild type SS18 by 78 amino acids of SSX genes (SSX1, SSX2 or SSX4) to form onco-protein SS18-SSX." (PMID 38678233, 2024). "Synovial sarcoma (SS) is a rare soft tissue sarcoma that occurs in adolescents and young adults, with a pathognomonic t (X; 18) (p11.2; q11.2) chromosomal translocation, fusing the SS18 (formerly known as SYT) gene with the SSX1, SSX2, or SSX4 gene." (PMID 35126101, 2021). "Synovial sarcoma is defined by a characteristic translocation t(X;18)(p11.2;q11.2), which is observed in > 95% of cases and results in the fusion of SS18 to the SSX1, SSX2, or SSX4 genes." (PMID 29415665, 2018). "It is characterized by the typical translocation t(X;18)(p11;q11) that generates the fusion between the synovial sarcoma translocation, chromosome 18 (SS18 or SYT) gene on chromosome 18 and either synovial sarcoma, X breakpoint 1, 2 or 4 (SSX1, SSX2 or SSX4) genes on the X chromosome." (PMID 21609503, 2011). "These proteins may function as transcriptional repressors; SSX1, SSX2 and SSX4 genes have been involved in the t (X;18) translocation characteristically found in all synovial sarcomas." (PMID 15715909, 2005). "Synovial sarcoma (SS) is a subtype of sarcomas characterized by a translocation between SSX18 and SSX1, SSX2, or SSX4." (PMID 40249565, 2025). "Cytogenetics also plays a significant role in synovial sarcoma as both monophasic and biphasic types are characterized by reciprocal chromosomal translocations (x;18)(p11.2;q11.2), translocating the SYT of chromosome 18 to either of the two homologous genes SSX1 or SSX2 on Xp11." (PMID 40964824, 2025). "Synovial sarcoma is a mesenchymal spindle cell tumor which displays variable epithelial differentiation and has a specific chromosomal translocation t(X; 18) (p11; q11), which results from the fusion of the SYT gene on chromosome 18 to exon 5 of either SSX1 or SSX2 genes on chromosome X." (PMID 29751751, 2018). "DNA sequencing showed that the fusion sites of all SS18-SSX1 and the four classical SS18-SSX2 tumors were involved in exon 10 of the SS18 gene (codon 410) and exon 6 of the SSX1 or SSX2 genes (codon 111), which is typical of the ordinary fusion site of synovial sarcoma." (PMID 27401493, 2016). "Specific translocation has helped to classify synovial sarcomas as they typically show a t(X;18) translocation with fusion between SSX1 and SYT genes with a biphasic appearance in two-thirds of cases whilst the remainder show a fusion between SSX2 and SYT genes." (PMID 19335917, 2009). "Synovial sarcoma harbors a t(X;18)(p11;q11) translocation that produces gene fusions between SS18 and SSX1, SSX2 or SSX4, that have not been identified in other neoplasms." (PMID 33921435, 2021).
sarcoma (15 papers, 2013 to 2025). A usually aggressive malignant neoplasm of the soft tissue or bone. "Most sarcoma-associated fusion genes such as SYT-SSX1/SSX2, BCOR-CCNB3, EWS-FLI1, PAX3-FOXO1 and COL1A1-PDGFB produce functional proteins." (PMID 25300797, 2014). "SS is characterized by the translocation of ss18 gene on chromosome 18 and synovial sarcoma x (SSX) gene on chromosome X (usually SSX1 or SSX2), which is the driving factor of tumorigenesis and leads to the expression of SS18-SSX fusion protein." (PMID 36003502, 2022). "SYT-SSX represents a sarcoma fusion protein that is expressed in synovial sarcoma secondary to the translocation of one of several highly homologous CTAs on chromosome X (SSX1, SSX2 and SSX4), and the SYT gene on chromosome 18, t(X;18)." (PMID 36765578, 2023). "The identification of fusion genes such as SYT-SSX1/SSX2, PAX3-FOXO1, TPM3/TPM4-ALK and EWS-FLI1 in human sarcomas has provided important insight into the diagnosis and targeted therapy of sarcomas." (PMID 25300797, 2014). "The identification of fusion genes such as SYT-SSX1/SSX2, PAX3-FOXO1, TPM3/TPM4-ALK, BCOR-CCNB3 and EWS-FLI1 in human sarcomas has provided important insight into the diagnosis and targeted therapy of sarcomas." (PMID 25300797, 2014). "We performed immunohistochemistry (IHC) on DDLS and WDLS to confirm protein expression of TTK, PBK and SPA17, as well as CTAs commonly expressed in sarcoma including NY-ESO-1 (included in Nanostring panel as CTAG1B), SSX2 and MAGE-A3, some of which that have been targeted by adoptive cell therapy." (PMID 38755218, 2024). "In synovial sarcoma, gene expression analysis revealed high levels of EGFR, SSX, ERBB2, IGFBP2, and IGF2 expression: this subtype of sarcoma is characterized by a translocation (X,18; p11,q11) which determines a fusion gene between SS18 and SSX1 (or SSX2) that exerts a key role in this neoplasm." (PMID 34207243, 2021). "However, there are also differences in the function of SSX2 and SYT-SSX2 in that only the latter has been shown to destabilize and reduce the overall levels of BMI1 in sarcoma cells, an effect not observed with SSX2 in melanoma cells." (PMID 25249625, 2014).
melanoma (14 papers, 2010 to 2024). A malignant, usually aggressive tumor composed of atypical, neoplastic melanocytes. "Staining of SSX2/3 in clinical specimens of melanoma demonstrated an association with chromatin that was confirmed by co-localization of SSX2 with chromatin in A375 melanoma cells during both inter- and metaphase." (PMID 25249625, 2014). "SSX2 further negatively regulates the level of the PcG-associated histone mark H3K27me3 in melanoma cells, and there is a clear inverse correlation between SSX2/3 expression and H3K27me3 in spermatogenesis." (PMID 25249625, 2014). "Here, we show that SSX2, a germline-specific protein ectopically expressed in melanoma and other types of human cancers, is a chromatin-associated protein that antagonizes BMI1 and EZH2 PcG body formation and derepresses PcG target genes." (PMID 25249625, 2014). "Expression analysis showed aberrant expression of SSX2 in various cancers including melanoma, colon cancer, hepatocellular carcinoma, and breast cancer." (PMID 38596293, 2024). "In melanoma cells, overexpression of SSX2 was shown to induce instability of pericentromeric heterochromatin in S-phase, and in breast cancer cells, SSX2 overexpression induced a senescence response in a S-phase dependent manner." (PMID 36276095, 2022). "The proteins are most frequently detected in melanoma, where approximately 40% of tumors are positive for SSX2, SSX3 or SSX4." (PMID 31963307, 2020). "We recently found that expression of SSX2 in A375 melanoma cells induced genomic instability in the form of micronuclei and chromatin bridges by an unidentified mechanism." (PMID 31114908, 2019). "We have demonstrated that knockdown of the SSX2 gene significantly reduced the proliferation of melanoma cells, consistent with another study showing that SSX proteins activate several important mitogenic signaling pathways, such as MAPK and Wnt." (PMID 27275820, 2016). "SSX2 expression has been documented on prostate cancer and in multiple myeloma in addition to melanoma." (PMID 24681846, 2014). "We correlated SSX expression with the presence of PcG nuclear bodies in a panel of melanoma cell lines and found that SSX2/3 (as determined by Mab E3 staining) was present in three of the nine cell lines (i.e. FM6, FM45 and FM79)." (PMID 25249625, 2014). "A role for SSX2 in inhibiting genome-wide H3K27me3 is further supported by increased levels of H3K27me3 upon SSX2 knockdown in melanoma cells and a clear inverse correlation between SSX2 and this histone mark in spermatogenesis." (PMID 25249625, 2014). "Together, these results document the development of a clinical grade reagent for TCR-based adoptive immunotherapy of human malignancies, targeting the cancer-testis antigen SSX2 using a codon-optimized TCR derived from a melanoma patient." (PMID 24681846, 2014). "SSX2 p103–111 was also shown to be a naturally presented SSX2 epitope by the recognition of SSX2+ SK-MEL-37 melanoma cell line and transfected COS7 cells by p103–11 peptide-specific CD8+ T cells." (PMID 20981248, 2010). "It was also shown that SSX2-specific CTL frequency increased with disease progression in at least one melanoma patient." (PMID 20981248, 2010). "Thus, instead of a direct correlation of SSX2 and Mediator complex levels, we investigated the potential deregulation of Mediator complex subunits in various cancer types, including breast cancer and melanoma, which often express SSX2 and other SSX proteins." (PMID 31695025, 2019). "Deletion of SSX2 in melanoma cells significantly reduced cell proliferation." (PMID 29190970, 2017). "Furthermore, members of the synovial sarcoma X breakpoint family (SSX) (melanoma growth promoters) were also down-regulated (e.g. SSX2, SSX4, and SSX4B) as a result of miR-4731 overexpression." (PMID 27331623, 2016).